MUC4 (mucin 4, cell surface associated)
Diseases named in the same sentence as MUC4 in open-access papers (continued):
Sharing a sentence is not in itself a finding about the gene and the disease.
lung carcinoma (31 papers, 2004 to 2025). "Its expression levels exhibit significant variation across different types of lung cancer; studies have demonstrated that elevated MUC4 expression is associated with adverse clinical outcomes in lung adenocarcinoma and lung squamous cell carcinoma." (PMID 40655139, 2025). "The accumulation of variants in exon 2 of MUC4 observed in our study is consistent with an earlier study in patients with lung cancer." (PMID 39338204, 2024). "The results showed that high expression of MUC4 was associated with a poor prognosis in ovarian cancer (HR = 1.14, p = 0.0335), brain cancer (HR = 1.42, p = 0.0312), and lung cancer (HR = 1.25, p = 0.0335)." (PMID 34336844, 2021). "Expression of certain mucins, such as MUC1 or MUC4, have been associated with lung cancer in other studies, and associated with poor prognosis for some patients." (PMID 31429720, 2019). "We also investigated potential interactions between tagSNPs of the MUC4 gene and cigarette smoking in lung cancer risk." (PMID 24204934, 2013). "Genotype frequencies of selected MUC4 SNPs among cases and controls and their association with lung cancer risk." (PMID 24204934, 2013). "Association between common MUC4 haplotypes in each block, and lung cancer risk in overall population and subpopulation stratified by pack-years of smoking." (PMID 24204934, 2013). "In this study, we performed a case-control study of 1,048 incident lung cancer cases and 1,048 age- and sex frequency-matched cancer-free controls in a Chinese population to investigate the role of MUC4 gene polymorphism in lung cancer etiology." (PMID 24204934, 2013). "As MUC4 acts as a tumor promoter for lung cancer, the variant allele G of rs3096337 or C of rs842461 exerts a greater adverse effect than that of the wild-type allele among heavy smokers." (PMID 24204934, 2013). "In the present case-control study, we investigated the effect of multiple common MUC4 gene variants and their interaction with cigarette exposure on lung cancer risk in a Southern Han Chinese population." (PMID 24204934, 2013). "MUC4 is a factor associated with a poor prognosis in various carcinomas and particularly in intractable carcinomas, such as pancreatobiliary and lung carcinomas." (PMID 19127263, 2009). "In conclusion, our study provides evidence that MUC4 polymorphisms and their interactions with smoking status may contribute to lung cancer etiology in a Chinese population." (PMID 24204934, 2013). "Our results suggest that MUC4 gene polymorphisms and their interaction with smoking may contribute to lung cancer etiology." (PMID 24204934, 2013). "The present work was motivated by the biological plausibility that genetic variation in MUC4 could alter its expression level or biochemical function and thus may have an impact on individual lung cancer risk." (PMID 24204934, 2013). "Stratified analyses between MUC4 rs863582 and rs842461 genotypes and lung cancer risk." (PMID 24204934, 2013). "MUC4 (identified by credible set eQTL associations for rs200460259), which encodes airway mucins is associated with severity of lung disease in cystic fibrosis (through functional annotation of another genome-wide signal) and risk of lung cancer (association with variants in the gene)." (PMID 34923368, 2022). "Because lung cancer is a multifactorial disease that likely involves multiple SNPs in genes, we assessed a broader spectrum of MUC4 variants individually as alleles and collectively as haplotypes, which may be more powerful than analyzing a single allele or locus." (PMID 24204934, 2013). "Yokoyama et al57 demonstrated that TET1-driven DNA hypomethylation regulated mucin 4 (MUC4) expression in lung cancer, with reduced TET1 levels leading to decreased MUC4 levels." (PMID 40520993, 2025). "Studies indicate that MUC4 expression is elevated in the presence of M2-TAMs, which enhances the stemness characteristics of lung cancer cells." (PMID 40655139, 2025).
lung carcinoma (continued). "Investigations into lung cancer cell lines have indicated that MUC4’s effect on ErbB signaling can lead to the activation of downstream pathways, including the MAPK and PI3K/Akt pathways." (PMID 40655139, 2025). "Specifically, an analysis of a patient cohort revealed that high MUC4 expression correlates with reduced overall survival (OS) rates among lung cancer patients, underscoring its prognostic significance." (PMID 40655139, 2025). "In lung cancer specifically, MUC4 expression aligns with histological subtypes, manifesting distinct patterns in NSCLC subtypes like adenocarcinoma, squamous cell carcinoma, and adenosquamous cell carcinoma." (PMID 40655139, 2025). "Overall, the role of MUC4 in lung cancer development is complex and multifaceted, involving significant interactions with various pathways and cell types within the TME." (PMID 40655139, 2025). "It has been shown that the well-known modifier of CF lung disease, Mucin 4 (MUC4) and Mucin 5AC (MUC5AC) are associated with lung cancer risk and prognosis, respectively." (PMID 34415821, 2022). "In the previous study, the downregulated genes CASP10 and CD177 and the upregulated genes BAK1, ST14, CD82, and MUC4 were detected as biomarkers for lung cancer by the joint sparse regression model." (PMID 35923697, 2022). "When considered together, our data demonstrated that MUC4 expression and promoter methylation status are potential prognosis biomarkers for lung cancer." (PMID 34336844, 2021). "Similar to MUC1, most of the previous studies on MUC4 have been directed at lung cancer whereas investigations into airway disorders are sparse." (PMID 32948202, 2020). "Here, we analyzed the gene expression datasets of human lung cancer and showed that MUC4 mRNA level in lung adenocarcinoma and lung squamous cell carcinoma tissues were significantly higher than that in normal lung tissues." (PMID 30683132, 2019). "We and others have investigated MUC4 biological roles in various cancers such as pancreatic, ovarian, esophagus and lung cancers." (PMID 30236127, 2018). "In conclusion, MUC4 immunohistochemistry is useful for differentiation of epithelioid mesothelioma from lung carcinoma, either adenocarcinoma or squamous cell carcinoma." (PMID 29317712, 2018). "This is the first report that TET1 mediated DNA hypomethylation regulates the expression of MUC4 in lung cancer." (PMID 28680536, 2017). "We showed a significant reduction of MUC4 mRNA by TET1 mRNA down-regulation in a lung cancer cell line." (PMID 28680536, 2017). "To identify a possible association of MUC4, MUC6, and MUC12 with lung cancer, we analyzed the publicly available The Cancer Genome Atlas (TCGA) exome sequence data for lung adenocarcinoma and lung squamous cell carcinoma." (PMID 24947164, 2014). "Earlier studies had shown that different subunits mediate the proliferative and survival functions of nicotine in lung cancer cells; it appears that α7, which is more relevant to cell proliferation, mediates the induction of MUC4 in these experiments." (PMID 22537161, 2012). "MUC4 was expressed particularly in lung carcinomas and, interestingly, it was proposed as a ligand for HER2, a growth factor receptor of the tyrosine kinase family, putatively implicated in hormonal escape of breast and prostate cancers." (PMID 14760390, 2004). "In addition, MUC4 suppressed the growth of lung cancer cells via the modulation of the cell cycle and the GSK3β/p-Akt protein." (PMID 40655139, 2025). "The level of MUC4 is elevated in lung cancer and it has been speculated to play various diverse roles in tumorigenesis." (PMID 32948202, 2020). "First, to the best of our knowledge, no study has evaluated MUC4 SNPs for associations with lung cancer." (PMID 24204934, 2013). "Taken together, these observations imply that MUC4 may promote tumor progression in human lung cancer pathogenesis." (PMID 24204934, 2013).
lung carcinoma (continued). "Overexpression of MUC1 and MUC4 in lung carcinomas may further contribute to REM pathogenesis." (PMID 40142939, 2025). "Likewise, MUC4 expression was down-regulated in all cancer types except for thyroid and lung cancer, indicating that it does not play a major role in causing colorectal cancer." (PMID 38544823, 2024). "The level of MUC4 is also elevated in lung cancer and may also play a role." (PMID 35205621, 2022). "However, the role of MUC4 in the occurrence and development of lung cancer seems controversial." (PMID 30683132, 2019). "Analysis of 591 lung carcinoma tumor exomes from The Cancer Genome Atlas (TCGA) revealed that 20% of non-small-cell lung cancer tumors in smokers have mutations in at least one of the MUC4, MUC6 or MUC12 genes in contrast to only 6% in non-smokers." (PMID 24947164, 2014). "It is biologically plausible that MUC4 may be involved in lung cancer etiology." (PMID 24204934, 2013). "In the lung cancer TME, MUC4 reinforces its influence through an array of biological functions, including the promotion of inflammation and immune evasion." (PMID 40655139, 2025). "Experimental validation confirmed the unique over-expression of predicted surface markers (MUC4, MSLN, and SLC7A11) in lung cancer cells at the protein level." (PMID 29560830, 2018). "So, MUC4 has the potential for the use as an additional negative marker of epithelioid mesothelioma for differentiation from lung cancer including adenocarcinoma or squamous cell carcinoma." (PMID 29317712, 2018). "The negative MUC4 expression showed 100% sensitivity, 86.2% specificity and accuracy rate of 91.2% to differentiate epithelioid mesothelioma from lung carcinoma." (PMID 29317712, 2018). "In addition, we found no MUC4 expression in mesothelial layer of visceral pleura present in 39 lung cancer cases." (PMID 29317712, 2018).
gastric cancer (28 papers, 2007 to 2025). A primary or metastatic malignant neoplasm involving the stomach. "Mucin 4 (MUC4) is a membrane-bound mucin glycoprotein that is frequently expressed in gastric cancers and associated with HER2." (PMID 39199625, 2024). "We found that MUC4 was significantly positively associated with the cell proliferation marker Ki-67 in individual cells from human subjects with gastric cancer." (PMID 37674528, 2023). "In early gastric cancer, expression of MUC4 was associated with lymphatic invasion, lymph node metastasis and predicted poor prognostic factors." (PMID 35255004, 2022). "Specifically, MUC4 mutation is also widely observed in pancreatic ductal adenocarcinoma and gastric cancer." (PMID 33714943, 2021). "Rare variants in MUC4 can be novel gastric cancer susceptibility loci in Koreans possessing the familial clustering of gastric cancer." (PMID 32701958, 2020). "The discovery of common variants in MUC4 region significantly linked with gastric cancer in a large case control cohort of gastric cancer supports the association of MUC4 with gastric cancer." (PMID 32701958, 2020). "Characteristics of the germline MUC4 variants associated with gastric cancer by linkage analysis in the 14 studied families." (PMID 32701958, 2020). "In gastric cancer, high expression of MUC4 and MUC1 is associated with poor patient prognosis." (PMID 39895782, 2025). "Finally, MUC4 expression was significantly associated with proliferation in human gastric cancer samples." (PMID 37674528, 2023). "We identified three rare variants in MUC4 associated with gastric cancer and 4 other cancer types." (PMID 32701958, 2020). "For example, miR-581-associated single-nucleotide polymorphisms located on the MUC4 3′UTR may reduce the interaction between miR-581 and MUC4 mRNA, promote the expression of oncoprotein MUC4, and be associated with the incidence of gastric cancer." (PMID 32899503, 2020). "In a larger cohort consisting of 597 GC patients and 9,759 healthy controls genotyped with SNP array, we discovered common variants in MUC4 regions (rs148735556, rs11717039, and rs547775645) significantly associated with GC supporting the association of MUC4 with gastric cancer." (PMID 32701958, 2020). "Similarly, the MUC4/MUC16/MUC20high group in stomach cancer showed a median survival of 762 days whereas the low risk had a median survival of 1811 days." (PMID 30236127, 2018). "A study on the combined expression pattern of MUC4 and other molecules like E-cadherin or other mucins may provide more accuracy and specificity to use MUC4 as a diagnostic or prognostic marker for gastric cancer." (PMID 18781152, 2008). "Overexpression of MUC4 was associated with an aggressive phenotype of gastric cancer cells." (PMID 18781152, 2008). "As we hypothesized that hereditary and sporadic gastric cancer may share genetic background for gastric cancer, we further analyzed whether variants of MUC4 are related to the development of GC in a large cohort which consists of 597 GC patients and 9759 healthy controls genotyped with SNP array." (PMID 32701958, 2020). "MUC4 high risk was also significantly associated with survival in bladder cancer (HR = 1.48), colon cancer (HR = 2.1), lung adenocarcinoma (HR = 1.7), lung squamous carcinoma (HR = 1.69), ovarian cancer (HR = 1.33), skin cancer (HR = 1.87) and stomach cancer (HR = 1.58)." (PMID 30236127, 2018). "Recent studies illustrated that MUC4 was correlated with prognosis of gastric cancer patients and promoted proliferation and invasion of gastric cancer cells." (PMID 34457026, 2021). "It was reported that the antioxidant alpha-lipoic acid inhibits the binding of STAT3 to the MUC4 promoter region to suppress the MUC4 expression and hence significantly reduces the proliferation of gastric cancers." (PMID 34394838, 2021).
gastric cancer (continued). "MUC4 upregulation has been reported to be involved in chemotherapy resistance of gastric cancer cells." (PMID 32604718, 2020). "We further validated in large populations of cases and controls and through expression analysis of MUC4 in normal gastric mucosa and gastric cancer tissues." (PMID 32701958, 2020). "ALA decreased STAT3 binding to MUC4 promoter region, repressed MUC4 expression, and consequently inhibited proliferation and invasion of human gastric cancer cells." (PMID 31915505, 2019). "To further explore the mechanism of ALA-mediated downregulation of MUC4, we cotransfected human gastric cancer cells with STAT3 siRNA and STAT3 overexpression construct." (PMID 31915505, 2019). "To identify the effect of ALA on the endogenous expression of MUC4 in human gastric cancer cells, we incubated AGS, BGC-823, and MKN-28 cells with 0, 0.5, 1, or 2 mM ALA for 24 h in RPMI with 10% FBS when cell confluence was 60%." (PMID 31915505, 2019). "The expression of MUC4 showed positive in 184 out of 240 gastric cancer tissues, while the expression of MUC4 showed positive in 80 out of 240 normal gastric tissues." (PMID 31915505, 2019). "Meanwhile, ALA reduced proliferation and invasion of human gastric cancer cells by suppressing MUC4 expression." (PMID 31915505, 2019). "ALA inhibits both proliferation and invasion of gastric cancer cells by suppression of STAT3-mediated MUC4 gene expression." (PMID 31915505, 2019). "ALA inhibited STAT3 binding to the MUC4 promoter region, reduced the expression of MUC4, which in turn inhibited the proliferation and invasion of gastric cancer cells." (PMID 31915505, 2019). "Many studies have shown that high MUC4 expression in the gastric cancer is related to the poor prognosis, such as lymph node metastasis and vascular invasion, which is the main cause of death in patients with gastric cancer." (PMID 31915505, 2019). "We performed immunohistochemistry staining, the results showed positive MUC4 expression in gastric cancer tissues compared with normal tissues (p < 0.001), which is in accordance with known study results." (PMID 31915505, 2019). "In summary, ALA inhibits proliferation and invasion of gastric cancer cells through downregulation of MUC4." (PMID 31915505, 2019). "We showed that the combination of MUC4, MUC16 and MUC20 signature is associated with statistically significant reduced overall survival and increased hazard ratio in pancreatic, colon and stomach cancer." (PMID 30236127, 2018). "This combination is associated with a poorer overall survival in different cancers including pancreatic, colon and stomach cancers suggesting MUC4/MUC16/MUC20 as a poor prognostic signature for these cancers." (PMID 30236127, 2018). "(A) Overall survival of MUC4/MUC16/MUC20 high and low risk groups in bladder cancer, colon cancer, lung adenocarcinoma, lung squamous adenocarcinoma, skin cancer and stomach cancer." (PMID 30236127, 2018). "In TCGA, We confirmed that MUC4 expression was observed mainly in human carcinomas including bladder, cervix, head and neck, lung, ovarian, pancreatic, prostate, stomach carcinomas." (PMID 30236127, 2018). "In conclusion, the expression of MUC4 as well as MUC1 in early gastric cancers is a useful marker to predict poor prognostic factors related with vessel invasion." (PMID 23152882, 2012). "Before the IHC study of the human specimens, we evaluated the specificity of the two MAbs by Western blotting and IHC of two MUC4 mRNA expressing gastric cancer cell lines." (PMID 23152882, 2012). "The relationship of MUC4 expression with the invasion of gastric cancers would be an interesting area of study." (PMID 23152882, 2012). "In conclusion, in the present study of early gastric cancers, MUC4/8G7, MUC4/1G8 and MUC1/DF3 expressions were observed mainly in well differentiated adenocarcinomas." (PMID 23152882, 2012).